LPAL2 (lipoprotein(a) like 2 (pseudogene))
Synonyms: APOARGC; formerly APOAL
Gene: Transcribed unprocessed pseudogene on chromosome 6 (160,453,428 to 160,511,007, reverse strand). Ensembl gene ENSG00000213071.
Subcellular location: Secreted
Diseases named in the same sentence as LPAL2 in open-access papers:
LPAL2 is named in the same sentence as 8 diseases in open-access papers, as found by Europe PMC text mining. Sharing a sentence is not in itself a finding about the gene and the disease. The quoted sentences say what the papers report.
glioma (2 papers, 2019 to 2022). A benign or malignant brain and spinal cord tumor that arises from glial cells (astrocytes, oligodendrocytes, ependymal cells). "Six pseudogenes (SP3P, ANXA2P3, PTTG3P, LPAL2, CLCA3P, and TDH) were reported to be associated with overall survival in glioma." (PMID 36333286, 2022). "A prior report that constructed another signature with six pseudogenes (SP3P, ANXA2P3, PTTG3P, LPAL2, CLCA3P, and TDH) for prediction of glioma patient survival." (PMID 31681595, 2019).
hepatocellular carcinoma (2 papers, 2022 to 2026). A malignant tumor that arises from hepatocytes. "Considering the inhibitory role of LPAL2 in the regulation of hepatocellular carcinoma stemness, this pseudogene-derived lncRNA can form the basis of a therapeutic strategy to target the CSC population." (PMID 41431719, 2026). "The knockdown of LPAL2 in hepatoma cells induced tumor formation, migration, invasion, sphere formation, and drug resistance." (PMID 36010685, 2022). "This analysis showed that LPAL2 expression was decreased in the doxorubicin-resistant hepatoma cell line, MHCC97L-Dox-R." (PMID 36010685, 2022). "Here, we found that knockdown of LPAL2 in hepatoma cells impaired doxorubicin-induced cell death by modulating the expression of apoptosis-related markers." (PMID 36010685, 2022). "Besides, a distinct group of hepatocellular carcinoma patients with high expression of LPAL2 and low expression of MMP9 showed a better survival rate." (PMID 41431719, 2026). "To address this question, we first assessed endogenous LPAL2 expression in hepatoma cell lines." (PMID 36010685, 2022). "Notably, LPAL2 expression was decreased in CD133-negative hepatoma cells, suggesting the involvement of LPAL2 in cancer stem cell-related functions." (PMID 36010685, 2022). "To date, the exact functional roles of LPAL2 in hepatoma remain unclear." (PMID 36010685, 2022). "In the current study, we found that the pseudogene-derived lncRNA LPAL2 is downregulated in hepatocellular carcinoma (HCC) tissues, and further showed that elevated LPAL2 expression is positively correlated with survival outcome." (PMID 36010685, 2022). "To verify this, we evaluated LPAL2 expression in hepatoma cell lines treated with or without doxorubicin, and found that LPAL2 expression was repressed by doxorubicin treatment in HA22T and Huh7 cell lines." (PMID 36010685, 2022).
cholangiocarcinoma (1 paper, 2018). A carcinoma that arises from the intrahepatic biliary tree (intrahepatic cholangiocarcinoma) or from the junction, or adjacent to the junction, of the right and left hepatic ducts (hilar cholangiocarcinoma). "Diagnostic value of lncRNAs for Cholangiocarcinoma: HULC(b), H19(c), LPAL2(d), C3P1(e), AC005550.3(f), APOC1P1(g), PVT1(h),and sensitivity: Sen." (PMID 30305026, 2018).
cancer (3 papers, 2021 to 2022). A tumor composed of atypical neoplastic, often pleomorphic cells that invade other tissues. "LPAL2 was identified as a pseudogene-derived lncRNA, but its functional role in cancer progression is limited." (PMID 36010685, 2022). "Collectively, these findings reveal that LPAL2 functions as a suppressor that represses stemness through the modulation of cancer stem cell marker expression." (PMID 36010685, 2022). "Notably, LPAL2 knockdown accelerated sphere formation, indicating that LPAL2 is involved in the cancer stem cell phenotype." (PMID 36010685, 2022). "Moreover, the cancer stem cell-related markers, Nanog, SOX2 and LIN28A, were induced by the depletion of LPAL2." (PMID 36010685, 2022). "Other cancer-related genes are ADAMTS17, LINC01748, LPAL2, SRP14-AS1 and WASH8P." (PMID 33672117, 2021).
tumor (3 papers, 2018 to 2024). "In our study, we established a novel role of LPAL2 in regulating tumor growth, metastasis, sphere formation, and drug resistance." (PMID 36010685, 2022). "Specifically, we showed that the knockdown of LPAL2 accelerates tumor growth and metastasis, and that MMP9 is directly regulated by LPAL2." (PMID 36010685, 2022). "Functionally, the knockdown of LPAL2 induces tumor growth, sphere formation, migration, and invasion." (PMID 36010685, 2022). "To determine how LPAL2 regulates tumor growth, cell migration, invasion and metastasis, we identified LPAL2-regulated target genes through microarray profiling analysis." (PMID 36010685, 2022). "Taken together, these findings support the conclusion that LPAL2 is a tumor suppressor in HCC." (PMID 36010685, 2022). "In this study, we found that LPAL2 acts as a tumor suppressor lncRNA in HCC cell lines." (PMID 36010685, 2022). "Our collective results indicate that LPAL2 acts as a tumor-suppressor lncRNA in HCC." (PMID 36010685, 2022). "The depletion of LPAL2 induced an increase in tumor growth and tumor weight." (PMID 36010685, 2022). "In conclusion, our findings advance the novel concept that LPAL2 is a tumor suppressor in HCC." (PMID 36010685, 2022). "Collectively, our findings establish LPAL2 as a novel tumor suppressor in HCC, and suggest targeting LPAL2 and MMP9 as a therapeutic approach for the treatment of HCC." (PMID 36010685, 2022). "In vitro and in vivo models support the conclusion that LPAL2 modulates tumor growth, metastasis and stemness phenotypes of HCC cell lines, and microarray profiling analysis and validation results suggest that LPAL2 regulates metalloproteinase-9 (MMP9) at the transcriptional level." (PMID 36010685, 2022).
LPAL2 also shares sentences with these, for which no sentence is quoted: cardiovascular diseases (1 paper); coronary artery disease (1); coronary stenosis (1).